NR4A2 (nuclear receptor subfamily 4 group A member 2)
Diseases named in the same sentence as NR4A2 in open-access papers (continued):
Sharing a sentence is not in itself a finding about the gene and the disease.
fetal growth restriction (2 papers, 2020 to 2021). A fetus that does not grow beyond the 10th percentile of conventionally accepted weight for gestational age. "Thus, we have validated the association between preterm fetal growth restriction and increased circulating mRNA coding NR4A2 and EMP1 (and possibly PGM5) in an independent cohort of samples from another continent." (PMID 32438913, 2020). "Nuclear Receptor Subfamily 4 Group A Member 2 (NR4A2) transcripts are elevated in the circulation of individuals whose pregnancies are complicated by preterm fetal growth restriction (FGR)." (PMID 34667209, 2021). "We validated the association between preterm fetal growth restriction and circulating EMP1, NR4A2, and PGM5 mRNA in a cohort from Europe." (PMID 32438913, 2020). "Given there was no change in NR4A2 expression in the pathological preterm placenta, we assessed whether the increased circulating levels of NR4A2 transcripts in pregnancies complicated by fetal growth restriction and preeclampsia might originate in the vasculature." (PMID 34667209, 2021). "To elucidate whether NR4A2 has a role in placental dysfunction, we investigated NR4A2 expression in placenta collected from pregnancies complicated by preterm preeclampsia and fetal growth restriction (≤ 34 weeks gestation), conditions that feature impaired placental development and dysfunction." (PMID 34667209, 2021). "The origin of elevated circulating NR4A2 transcripts in patients with preterm fetal growth restriction and preeclampsia remains unknown, but is unlikely to be from the placenta." (PMID 34667209, 2021). "Although we found that placental NR4A2 expression is not altered with preterm preeclampsia or fetal growth restriction, the gene does regulate several important intracellular pathways associated with oxidative stress, fetal growth, and inflammation under the dysfunctional condition of hypoxia." (PMID 34667209, 2021). "Although we identified increased NR4A2 transcripts in the maternal circulation of pregnancies complicated by fetal growth restriction, the previous paper did not identify whether the transcripts originated from the dysfunctional placenta." (PMID 34667209, 2021).
inflammatory bowel disease (2 papers, 2019 to 2023). A spectrum of small and large bowel inflammatory diseases of unknown etiology. "Nevertheless, apart from its role in modulating Treg cell function, NR4A2 has also been shown to regulate vitamin D metabolism, Th17 cell differentiation, and microbiota homeostasis in some inflammatory autoimmune diseases, such as inflammatory bowel disease and Graves’ diseases." (PMID 38006062, 2023).
ischemic stroke (2 papers, 2017 to 2023). A stroke disorder caused by obstruction of blood flow to the brain, due to thrombotic (local blood clot formation) or embolic (due to a blood clot or other material traveling from another site) event. "For example, in rat models of ischemic stroke, NR4A2 was found to be regulated by miR-145-5p, and anti-miR-145-5p treatment enhanced neurological recovery following reperfusion." (PMID 37887305, 2023).
mental disorder (2 papers, 2021 to 2025). A disease that has its basis in the disruption of mental process. "This revision encourages us to continue to further explore the diverse mechanisms that regulate NR4A2 expression in different diseases and disorders, including those associated with neurodevelopmental, neurodegenerative, addiction, and mental disorders." (PMID 41009723, 2025).
metabolic syndrome (2 papers, 2020 to 2025). A cluster of metabolic risk factors for CARDIOVASCULAR DISEASES and TYPE 2 DIABETES MELLITUS. "Additionally, Nr4a2 has been reported to regulate cardiac fibrosis by inducing autophagic flux and inhibiting apoptosis in myocardial injury associated with metabolic syndrome (MetS)." (PMID 41007655, 2025).
placental insufficiency (2 papers, 2020 to 2021). Failure of the placenta to deliver an adequate supply of nutrients and oxygen to the fetus. "Knockdown of NR4A2 under hypoxia significantly increased expression of NLR family pyrin domain containing 3 (NLRP3), a master regulator of the inflammasome (p = 0.0065) and Serine Peptidase Inhibitor, Kunitz Type 1 (SPINT1), associated with placental insufficiency (p = 0.0056)." (PMID 34667209, 2021).
preeclampsia (2 papers, 2021 to 2024). Preeclampsia is a hypertensive disorder of pregnancy that is characterized by new-onset hypertension with proteinuria presenting after 20 weeks of gestation, and depending on mild or severe forms may initially present with severe headache, visual disturbances, and hyperreflexia. "We next assessed the effects of NR4A2 knockdown on sFlt-1, an anti-angiogenic factor increased in preeclampsia, and placental growth factor (PGF), an angiogenic factor decreased in preeclampsia." (PMID 34667209, 2021). "We found significantly increased circulating NR4A2 transcripts in the growth restricted cases with preeclampsia, compared to normotensive cases." (PMID 34667209, 2021). "In this paper, we show that the cases with preeclampsia (PE) have increased circulating NR4A2 transcripts compared to those with normotensive FGR." (PMID 34667209, 2021). "However, we also found that silencing NR4A2 increased the expression of NLRP3, which is a key regulator of the inflammatory response and has been implicated in preeclampsia pathogenesis." (PMID 34667209, 2021). "However, we have yet to distinguish whether placental NR4A2 may have a role in late-onset preeclampsia, as we only assessed NR4A2 levels in samples collected from early-onset cases of preeclampsia with preterm delivery (≤ 34 weeks)." (PMID 34667209, 2021). "Interestingly, the placenta does not appear to be the source of higher maternal circulating NR4A2 mRNA, as the authors did not detect differential expression of NR4A2 in placental tissue with IUGR or preeclampsia." (PMID 38534344, 2024).
psychosis (2 papers, 2008 to 2017). "Another gene down-regulated in psychosis is the transcription factor Nurr1 (NR4A2), an orphan nuclear receptor associated with the development of dopaminergic cells in the mid-brain (p < 0.00001, FC-1.16)." (PMID 18992145, 2008). "Most individual studies show consistent down-regulation of NR4A2 gene, except the study 4, and the combined analysis at the bottom indicates that NR4A2 gene is significantly down-regulated in psychosis." (PMID 18992145, 2008). "We have also confirmed that expression of the neuropeptide genes are down-regulated in psychosis; NPY (p = 0.02, FC -1.32), NR4A2 (p = 0.01, FC -1.39), SST (p = 0.001, FC -1.57) and TAC1 (p = 0.01, FC -1.6)." (PMID 18992145, 2008). "A nuclear receptor subfamily 4, group A, member 2 (NR4A2) gene was also down-regulated (p = 0.00001, FC -1.16) in psychosis." (PMID 18992145, 2008).
pterygium (2 papers, 2009 to 2022). A wedge-shaped fibrovascular lesion arising from the bulbar conjunctiva and extending to the cornea. "NR4A2 encodes a nuclear receptor of the steroid-thyroid hormone-retinoid receptor family and may be involved in pterygium once it is associated with cellular response to oxidative stress and regulation of apoptotic signaling pathway." (PMID 34997134, 2022). "IGFBP3, present in un-involved conjunctival stroma and epithelium, and NR4A2, present in conjunctival epithelium, were reduced in pterygium." (PMID 19272163, 2009). "Our results show that protein expression levels for keratin 6, CEACAM5, CD24, MSMB and MUC5AC were increased, whereas NR4A2 and IGFBP3 were reduced in pterygium, consistent with the transcript changes detected by the microarray analysis." (PMID 19272163, 2009).
triple-negative breast carcinoma (2 papers, 2025). An invasive breast carcinoma which is negative for expression of estrogen receptor (ER), progesterone receptor (PR), and human epidermal growth factor receptor 2 (HER2). "This study is based on the hypothesis that orphan nuclear receptor 4A1 (NR4A1) and NR4A2 maintain low levels of ferroptosis in triple negative breast cancer (TNBC) cells and bis-indole derived (CDIM) compounds act as NR4A1/2 ligands that induce ferroptosis by enhancing CD71 expression." (PMID 41184246, 2025). "This study is based on the hypothesis that orphan nuclear receptor 4A1 (NR4A1) and NR4A2 maintain low levels of ferroptosis in triple negative breast cancer (TNBC) cells and that bis-indole derived (CDIM) compounds act as NR4A1/2 ligands that induce ferroptosis by enhancing CD71 expression." (PMID 40313760, 2025).
vitamin D deficiency (2 papers, 2018 to 2025). A nutritional condition produced by a deficiency of VITAMIN D in the diet, insufficient production of vitamin D in the skin, inadequate absorption of vitamin D from the diet, or abnormal conversion of vitamin D to its bioactive metabolites. "This systematic review consolidates evidence for genetic (e.g., NR4A2, TBX1, MTHFR) and environmental (e.g., phthalates, consanguinity, vitamin D deficiency) risk factors in Saudi ASD populations, while highlighting neuroinflammation as a potential biomarker." (PMID 41246720, 2025).
adenoid cystic carcinoma (1 paper, 2020). A malignant tumor arising from the epithelial cells. "However, unlike fusion transcripts that occur in other salivary gland tumors, which result in the production of fusion proteins like the MYB-NFIB fusion genes produced in adenoid cystic carcinoma, in this case the result is a more highly transcribed NR4A3 or NR4A2 gene, but no fusion proteins." (PMID 32867110, 2020).
adenosquamous carcinoma (1 paper, 2014). A carcinoma composed of malignant glandular cells and malignant squamous cells. "We detected MAML2 rearrangement using fluorescence in situ hybridization (FISH) in tissue samples from 42 cases of PMEC and 40 of adenosquamous carcinoma (ASC), and the expression of potential downstream targets of MECT1-MAML2, including HES1, FLT1 and NR4A2 with immunohistochemistry (IHC)." (PMID 24714697, 2014).
brain cancer (1 paper, 2017). A primary or metastatic malignant neoplasm affecting the brain. "At least five of them (ARNT2, NEUROD1, NR1I2, HOXC9, NR4A2) are associated with brain cancer in previous studies." (PMID 29033978, 2017).
cervical tumor (1 paper, 2017). "According to the available data in the Human Protein Atlas, most of tested cervical tumor samples were positive for protein expression of EGR3, NR4A2, SOX9, PA2G4, ENO1, and TEAD4." (PMID 28670312, 2017).
cervicitis (1 paper, 2024). An acute or chronic inflammatory process that affects the cervix. "NR4A3 was significantly expressed in CIN I (p < 0.05) and NR4A2 was expressed in both cervicitis and CIN III (p > 0.05)." (PMID 39639963, 2024). "On the other hand, the receptor NR4A2 was expressed in cervicitis and CIN III, with a tendency to underexpression in CIN I, a result that was not statistically significant." (PMID 39639963, 2024).
cocaine abuse (1 paper, 2010). Disorders related or resulting from use of cocaine. "Relatively little research currently associates NR4A2 with BD, lithium response, or cocaine abuse." (PMID 21092101, 2010).
coronary artery calcification (1 paper, 2025). Calcification of the coronary artery, used as a measure of coronary atherosclerosis, a risk factor for myocardial infarction. "Although studies on NR4A2 in vascular calcification are limited, a prospective population-based study reported that NR4A2 haplotypes may be associated with increased aortic and coronary artery calcification, although the underlying mechanisms remain unclear." (PMID 41438090, 2025).
developmental and epileptic encephalopathy (1 paper, 2024). An epilepsy associated with developmental impairment that may be due to either the underlying etiology or the superimposed epileptic activity, or both. "According to these findings, we propose that NR4A2 should be considered as a first-tier candidate gene for study in patients with suspected developmental and epileptic encephalopathy." (PMID 38791237, 2024).
Down syndrome (1 paper, 2022). "In 14 patients, the presence of Lewy bodies was examined, with positive findings in six cases (42.9%): 22q11.2 deletion syndrome (n = 2/3), Down syndrome (n = 2/2), NR4A2 (n = 1/1) and RAB39B (n = 1/1)." (PMID 36699000, 2022).
early-onset dystonia parkinsonism (1 paper, 2022). "In previous studies, variants in NR4A2 have also been associated with early-onset dystonia parkinsonism." (PMID 35992907, 2022).
endometriosis (1 paper, 2025). The growth of functional endometrial tissue in anatomic sites outside the uterine body. "Thus, DIM-3,5 derivatives simultaneously suppress NR4A1- and NR4A2-dependent endometriosis progression effectively and represent a promising non-hormonal therapeutic strategy to replace current hormone-based treatments, that can be associated with adverse effects." (PMID 41002243, 2025).
Epileptic encephalopathy (1 paper, 2024). A condition in which epileptiform abnormalities are believed to contribute to the progressive disturbance in cerebral function. "Accordingly, we propose that NR4A2 should be considered as a first-tier target gene for the genetic diagnosis of developmental and epileptic encephalopathy." (PMID 38791237, 2024).
fatty liver (1 paper, 2023). "Further analysis demonstrated that two genes, including NR4A2 and IGFBP1b with higher AUC, sensitivity, and specificity, were diagnostic biomarkers in fatty liver." (PMID 37993474, 2023). "We reported NR4A2 and IGFBP1b as novel diagnostic biomarkers in fatty liver." (PMID 37993474, 2023).
focal dystonia (1 paper, 2025). A dystonia that is localized to a specific part of the body. "For KLC1 and NR4A2, five and four additional patients, respectively, with similar phenotypes of adult‐onset focal dystonia, carried VUS." (PMID 40533913, 2025).
fragile X syndrome (1 paper, 2025). A genetic syndrome caused by mutations in the FMR1 gene which is responsible for the expression of the fragile X mental retardation 1 protein. "All affected NR4A2 subjects (probands and siblings) tested normal for fragile X syndrome and common ASD/NDD-associated genetic variants." (PMID 40564942, 2025).
gastric adenocarcinoma (1 paper, 2013). "Our principal findings are that gastrin regulates NR4A2 expression and activity in gastric adenocarcinoma AGS-GR cells." (PMID 24086717, 2013). "Collectively, our results uncover a role of NR4A2 in gastric adenocarcinoma cells, and suggest that both the level and the localization of NR4A2 protein are of importance regarding the cellular responses of these cells." (PMID 24086717, 2013). "Collectively, our study suggests a function of NR4A2 concurrent with a tumor suppressor role in gastric adenocarcinoma cells." (PMID 24086717, 2013). "To further substantiate the relevance of our findings in vivo, we analyzed the protein expression of NR4A2 in a small collection of gastric adenocarcinomas (intestinal n=3, diffuse n=3) by immunohistochemistry." (PMID 24086717, 2013). "We further examined the role of NR4A2 in gastrin induced responses by employing the gastric adenocarcinoma cell line AGS-GR Gastrin induced a ~8-fold induction of NR4A2 mRNA in AGS-GR cells, followed by a rapid decrease to baseline after ~4 h of stimulation." (PMID 24086717, 2013). "We conclude that gastrin induced NR4A2 expression and transactivation play an important role in gastric adenocarcinoma cells." (PMID 24086717, 2013). "A better understanding of gastrin–NR4A2 regulated processes may reveal new strategies to treatment of gastric adenocarcinomas." (PMID 24086717, 2013). "In this study we examined the role of NR4A2 in the gastric adenocarcinoma cells." (PMID 24086717, 2013). "In accordance with this, we also observed changed NR4A2 expression in gastric adenocarcinomas, seemingly being dominated by a general expression in tumor cells compared to the mainly strong NR4A2 expression in the gastrin responsive neuroendocrine ECL cells in normal mucosa." (PMID 24086717, 2013). "Thus it was of interest to examine whether NR4A2 would influence gastrin induced migration and invasion in our gastric adenocarcinoma cells." (PMID 24086717, 2013). "In vivo, NR4A2 is strongly expressed in the gastrin responsive neuroendocrine ECL cells in normal mucosa, whereas gastric adenocarcinoma tissue reveals a more diffuse and variable expression in tumor cells." (PMID 24086717, 2013). "Whether NR4A2 is involved in a corresponding mechanism in gastric adenocarcinoma cells is not known." (PMID 24086717, 2013).
Gaucher disease (1 paper, 2021). Gaucher disease (GD) is a lysosomal storage disorder encompassing three main forms (types 1, 2 and 3), a fetal form and a variant with cardiac involvement (Gaucher disease - ophthalmoplegia - cardiovascular calcification or Gaucher-like disease). "We found numerous transcription factors that are putative regulators of cytokine expression in a cell-specific context, such as the signaling axes controlled by STAT2, JUN, and NR4A2 as candidate regulators of the monocyte Gaucher disease cytokine network." (PMID 34490253, 2021).
glioma (1 paper, 2022). A benign or malignant brain and spinal cord tumor that arises from glial cells (astrocytes, oligodendrocytes, ependymal cells).
head and neck squamous cell carcinoma (1 paper, 2016). A squamous cell carcinoma that arises from any of the following anatomic sites: lip and oral cavity, nasal cavity, paranasal sinuses, pharynx, larynx, and salivary glands. "In addition to recurrent integrations in RAD51B, NR4A2, and TP63, additional genomic alterations were found in receptor tyrosine kinases, primarily FGFR2 and FGFR3, in HPV-positive head and neck squamous cell carcinoma." (PMID 27154171, 2016).
Hypertension (1 paper, 2025). The presence of chronic increased pressure in the systemic arterial system. "The NR4A2 gene has been reported to be important for cytokine regulation and may contribute to inflammation in the renal medulla in hypertension; the activation of NR4A2 in response to angiotensin II is further modulated by SIK1." (PMID 41169019, 2025).
intestinal tumours (1 paper, 2023). "As a cyclo-oxygenase-2 inhibitor, parecoxinib was found to reduce OPN expression through blockade of the nuclear receptor subfamily 4 group A member 2 (NR4A2) and Wnt signalling pathways, in intestinal tumours of mice." (PMID 36672705, 2023).
ischemic heart diseases (1 paper, 2018). "Here, we aimed to clarify the function of NR4A2 in cardiomyocyte apoptosis and autophagy in order to determine whether it is a potential therapeutic target for ischemic heart diseases." (PMID 29531824, 2018).
lung squamous cell carcinoma (1 paper, 2023). "Analyzing gene expression data for non‐cancerous lung tissues in the TCGA cohorts of LUAD and lung squamous cell carcinoma, we observed significant positive correlations between age and expression level of NR4A2." (PMID 37428471, 2023).
lymphoma (1 paper, 2023). A malignant (clonal) proliferation of B- lymphocytes or T- lymphocytes which involves the lymph nodes, bone marrow and/or extranodal sites. "Interestingly, NR4A2 has been reported as a tumor suppressor in lymphoma." (PMID 36831639, 2023).
mantle cell lymphoma (1 paper, 2023). Mantle cell lymphoma is a rare form of malignant non-Hodgkin lymphoma affecting B lymphocytes in the lymph nodes in a region called the ``mantle zone''. "Of interest is also an observation in our lab that ERβ interacts with the promoter region of NR4A2 in the genome of the mantle cell lymphoma cell line Granta-519, as determined by genome-wide chromatin immunoprecipitation." (PMID 36831639, 2023).
myxoid chondrosarcoma (1 paper, 2024). A chondrosarcoma characterized by the presence of myxoid changes. "NR4A2 may functionally replace NR4A3, the usual 3′ partner in extraskeletal myxoid chondrosarcoma." (PMID 38339014, 2024).